OR1J1 (olfactory receptor family 1 subfamily J member 1)
Description:
Odorant receptor.
Synonyms: hg32; OR9-18
Tractability: Small molecule: it belongs to a druggable protein family. Antibody: UniProt places it where antibodies can reach, with high confidence; UniProt predicts a signal peptide or a membrane-spanning region; its Gene Ontology location is reachable by antibodies, with medium confidence.
Gene: Protein-coding gene on chromosome 9 (122,476,958 to 122,477,926, reverse strand). Ensembl gene ENSG00000136834.
Subcellular location: Cell membrane
Pathways (Reactome):
Sensory Perception: Expression and translocation of olfactory receptors
Gene Ontology:
Molecular function: olfactory receptor activity; G protein-coupled receptor activity
Biological process: signal transduction; detection of chemical stimulus involved in sensory perception of smell; G protein-coupled receptor signaling pathway
Cellular component: plasma membrane; membrane
Genetic constraint (gnomAD): Loss-of-function variants: 1 observed, 0.76 expected, observed/expected ratio (o/e) 1.32, 90% interval 0.3 to 1.91. That is too few expected variants to judge how well the gene tolerates losing a copy. Missense variants: 382 observed, 399.21 expected, observed/expected ratio (o/e) 0.96, 90% interval 0.88 to 1.04. Synonymous variants: 159 observed, 160.63 expected, observed/expected ratio (o/e) 0.99, 90% interval 0.87 to 1.13.
Homologues: Orthologues: macaque OR1J1 (91% identical), rabbit OR1J1 (79% identical), rat Or1j1 (77% identical), mouse Or1j1 (76% identical), guinea pig OR1J1 (75% identical). Paralogues in human: OR1J2 (72% identical), OR1J4 (72% identical), OR1E2 (56% identical), OR1E1 (56% identical), OR1F1 (56% identical), OR1M1 (52% identical), OR7D2 (52% identical), OR1N1 (51% identical), OR7C1 (51% identical), OR1L4 (50% identical), OR7A17 (50% identical), OR1G1 (50% identical), and 116 more.